ENSG00000253013
Gene: Small nucleolar RNA gene on chromosome 4 (186,130,021 to 186,130,155, forward strand). Ensembl gene ENSG00000253013.
Homologues: Paralogues in human: SNORA31B (71% identical), SNORA31 (55% identical).